NLRP3 (NLR family pyrin domain containing 3)
Diseases named in the same sentence as NLRP3 in open-access papers (continued):
Sharing a sentence is not in itself a finding about the gene and the disease.
viral infection (continued). "Thus, highlighting the role of NLRP3 inflammasome during HMPV infection may provide a new perspective on the prevention and treatment of this viral disease." (PMID 30964929, 2019). "However, other studies reported that MAVS is required for NLRP3 inflammasome activation by viral infections, but not by non-viral NLRP3 stimuli." (PMID 31284572, 2019). "Although the authors did not evaluate virus infection directly, Trim31-deficient cells stimulated with poly(I:C) express higher levels of NLRP3 compared to wild-type cells suggesting TRIM31 may regulate NLRP3 downstream of virus recognition." (PMID 28829373, 2017). "In the meantime, whether NLRP3 could affect RVFV viral replication in the mouse model during later time-point could be investigated in the future study, since later downstream inflammatory responses mediated through NLRP3 could potentially affect viral infection." (PMID 39213434, 2024). "Furthermore, studies suggest that the reduction of IL-1β and inhibition of the NLRP3 inflammasome could impair the anti-viral immune response, exposing patients with IL-1β and NLRP3 inhibition to a more severe course of a viral infection than those without." (PMID 36905446, 2023). "Complications such as continuous stimuli or viral infections, such as the SARS-CoV-2 infection, may worsen the prognosis of TBI, altering the immune response and increasing the neuroinflammatory processes related to NLRP3, whose activation occurs both in TBI and in SARS-CoV-2 infection." (PMID 32867310, 2020). "Furthermore, simultaneous inhibition of apoptosis and necroptosis did not alter ASC speck formation or ASC oligomerization, indicating that NLRP3 activation in the context of cytopathogenic virus infection is independent of these forms of programmed cell death." (PMID 31024004, 2019). "In contrast to its role in viral infection, RACK1 protects cells from infection byPasteurella multocida, a gram-negative bacterium, via activation of the NLRP3 inflammasome." (PMID 38813597, 2024). "Although the NLRP3 inflammasome-mediated IL-1β production plays an essential role in viral infection, there are no mechanism studies on SVA that induce NF-κB and NLRP3 activation in vitro or in vivo." (PMID 35254168, 2022). "Of the PRRs, the protein levels of AIM2 increased over time only with viral infection, whereas the levels of IFI16 and NLRP3 showed no remarkable change." (PMID 28369146, 2017). "However, it is not clear if NLRP3 inflammasome activation participates in the pathogenesis of viral fulminant hepatitis (FH), a clinical severe syndrome characterized by acute inflammation in the liver along with massive necrosis of hepatocytes and hepatic encephalopathy during viral infection." (PMID 26367131, 2015). "Unlike NLRP3, NLRP12 expression is decreased in human macrophages following viral infections (e.g., ZIKV, dengue virus [DENV], and Japanese encephalitis virus [JEV]); it exerts antiviral properties and interacts with NLRP3 to block the activation of the human NLRP3 inflammasome." (PMID 38932258, 2024). "Notably, most of these studies overexpressed NLRP3 mutants lacking the LRR domain by transfection or viral infection or replaced the LRR domain of the endogenous NLRP3 protein with a large LacZ protein, which may interfere with NLRP3 function." (PMID 36403854, 2022).
ischemic stroke (220 papers, 2014 to 2026). A stroke disorder caused by obstruction of blood flow to the brain, due to thrombotic (local blood clot formation) or embolic (due to a blood clot or other material traveling from another site) event. "The neuroprotective mechanisms are associated with regulations of TLR4/NF-κB/NLRP3/ caspase-1 and caspase-3 signals, as well as Bcl-2/Bax ratio, suggesting SO is a novel neuroinflammatory regulator in ischemic stroke." (PMID 40289983, 2025). "The activation of the NLRP3 inflammasome is intricately associated with neuroinflammation and neurodegeneration, thereby exacerbating brain damage following ischemic stroke." (PMID 40160465, 2025). "The results showed that serum NLRP3 levels had a certain diagnostic value for POCD in elderly patients with ischemic stroke, with an AUC of 0.805, a cutoff value of 7.92 ng/mL, sensitivity of 73.0%, and specificity of 74.7%." (PMID 40417311, 2025). "The results revealed that HR at T3, MAP at T3, preoperative NLRP3, IL-6, IL-17 levels, and esketamine treatment were all risk factors for cognitive dysfunction in elderly patients undergoing general anesthesia for ischemic stroke." (PMID 40417311, 2025). "Increasing evidence has implicated that activation of NLRP3 inflammasome in ischemic stroke regulates neuroinflammation and neuronal cell death, while inhibition of NLRP3 attenuates neurological deficits and infarct volumes." (PMID 38178174, 2024). "-Increased risk of adult-onset Still’s disease.-Increased risk of gastric cancer.-Increased risk of ischemic stroke combined with NLRP3 rs10754558." (PMID 38920661, 2024). "Some studies have reported that the P2RX7/NLRP3 pathway caused neuronal pyroptosis after ischemic stroke in mice." (PMID 38965602, 2024). "The NLRP3 inflammasome has a major role in the BBB disruption caused by ischemic stroke, triggering inflammatory pathways and causing pyroptosis in brain endothelial cells." (PMID 36937182, 2023). "Our results substantiated that the NLRP3 inflammasome was activated in astrocytes, causing astrocyte pyroptosis during ischemic stroke." (PMID 37353794, 2023). "A total of 601 publications associated with NLRP3 in ischemic stroke were retrieved from WoSCC, 453 articles, and 141 reviews." (PMID 37088947, 2023). "Multiple studies have reported that the activation and expression of NLRP3 inflammasome fosters the progression of athero-, arterio-, and/or arteriolosclerosis lesions, hence increasing the risk for ischemic stroke." (PMID 36676165, 2023). "Caspase-1, an inflammasome-activated NLRP3 enzyme capable of lysing other proteins, is also implicated in the pathophysiology of ischemic stroke." (PMID 36297283, 2022). "A recent study indicated that NLRP3 inflammasome deficiency or using its selective inhibitor (MCC950) can improve cerebral injury after ischemic stroke." (PMID 35497095, 2022). "An increasing number of studies have linked oxidative stress to NLRP3 inflammasome activation during ischemic stroke." (PMID 35403328, 2022). "Activation of the NLRP3 inflammasome is also strongly associated with immunotherapy after ischemic stroke." (PMID 36685518, 2022). "NLRP3-deficient mice received reducing infarcts and less damage on brain-blood-barrier after ischemic stroke via the examination of magnetic resonance imaging." (PMID 36204568, 2022). "In our study, the levels of inflammatory factors including NLRP3, Caspase-1, and IL-1β were elevated in the MCAO group, demonstrating that the NLRP3 inflammasome was associated with the development of ischemic stroke." (PMID 36262547, 2022). "Previous studies have shown that NLRP3 inflammasome activation participates in the underlying molecular pathway of ischemic stroke in diabetic mice and retinal ischemic/reperfusion injury." (PMID 34305534, 2021).
ischemic stroke (continued). "Studies have shown that NLRP3 deficiency can improve the neurovascular damage in experimental ischemic stroke." (PMID 35008558, 2021). "Of note, previous studies have shown that inhibiting NLRP3 inflammasome activation is an effective means to alleviate the damage associated with ischemic stroke and retinal ischemia." (PMID 34305534, 2021). "In this review, we describe the composition and activation of the NLRP3 inflammasome in ischemic stroke and the molecules involved in associated inflammatory pathways." (PMID 34059091, 2021). "Among all potential targets, NLRP3 is the most recognized and widely implicated regulator in ischemic stroke." (PMID 34233704, 2021). "Deficiency of NLRP3 significantly alleviated neuroinflammation in ischaemic stroke and ischaemic injury." (PMID 32990414, 2020). "The expression level changes and abnormal gene mutation of coding components of NLRP3 can impact NLRP3-regulated inflammatory response, thus disturbing the immune balance of the internal environment and the occurrence of ischemic stroke." (PMID 32581721, 2020). "This was consistent with the previous studies, which demonstrated the detection of NLRP3 inflammasome in the cytoplasm of cerebral cortical neurons and was associated with the incidence and progression of ischemic stroke." (PMID 31117961, 2019). "NACHT, LRR, and PYD domains-containing protein 3 (NLRP3) inflammasomes are associated with inflammatory responses and cellular injury after ischemic stroke or ICH." (PMID 29970985, 2018). "With NLRP3 knockout mice, Yang's group found that NLRP3 deficiency reduced cerebral injury after ischemic stroke, including the reduction of cerebral infarction volume, cerebral edema, and brain barrier permeability." (PMID 29853850, 2018). "Furthermore, this study elucidated the intricate interplay between UA and the NF-κB pathway as well as NLRP3-mediated pyroptosis, thereby enhancing our understanding of the mechanisms underlying UA-mediated neuroprotection after ischemic stroke." (PMID 40717974, 2025). "The objective of this study is to demonstrate the therapeutic impact of UA in CIRI and to investigate whether the molecule mechanism of UA is associated with NF-κB/NLRP3-mediated microglia pyroptosis and neuroinflammation in ischemic stroke." (PMID 40717974, 2025). "Growing evidence implicates elevated serum NLRP3 inflammasome levels as a potential predictor for malignant cerebral oedema post-ischemic stroke, though this association requires further validation in large-scale studies to account for potential confounding by stroke severity." (PMID 41408503, 2025). "Importantly, there was also a significant decrease in ischemic stroke damage in the NLRP3-deficient mice with chronic opioid exposure as compared with wild-type controls." (PMID 39753298, 2025). "We then evaluated ischemic stroke outcomes in the NLRP3-deficient mice." (PMID 39753298, 2025). "Moreover, inhibiting Bruton’s tyrosine kinase (BTK), an upstream activator of the NLRP3 inflammasome, can reduce the infarct volume and associated neurological damage following ischemic stroke." (PMID 40075143, 2025). "Hence, the NF-κB/NLRP3 inflammasome signaling pathway is a key signaling pathway associated with ischemic stroke." (PMID 39199474, 2024). "Ischemic stroke and cardiomyopathies have been clearly linked to NLRP3 inflammasome activation." (PMID 38816358, 2024). "In addition, the NLRP3 inflammasome inhibitor MCC950 suppressed the inflammatory response of BBB disruption caused by ischemic stroke." (PMID 36937182, 2023). "However, the underlying mechanism between the immunoproteasome and NLRP3 inflammasomes under ischaemic stroke conditions remains to be established." (PMID 34866334, 2022). "The NF-κB and NLRP3 inflammasomes are required to initiate inflammation, and the effects of ROS may also be Nrf2-dependent, and both are implicated in the mechanism of ischemic stroke." (PMID 36232980, 2022).
ischemic stroke (continued). "Thus, the dysregulation of the NLRP3 inflammasome is associated with various diseases, including ischemic stroke, diabetes, multiple sclerosis, atherosclerosis, Alzheimer’s disease, and other inflammatory-related diseases." (PMID 35955939, 2022). "The NLRP3 inflammasome regulates the release of pro-inflammatory factors IL-1β and IL-18, one of the critical steps leading to neuronal cell death associated with ischemic stroke." (PMID 36232980, 2022). "Furthermore, some studies have suggested that the NLRP3 gene polymorphisms are related to the occurrence of ischemic stroke, providing significant clinical evidence linking NLRP3 and the risk of ischemic stroke." (PMID 35403328, 2022). "Understanding the NLRP3 inflammasome may provide novel ideas and approaches because targeting of upstream and downstream molecules in the NLRP3 pathway shows promise for ischemic stroke therapy." (PMID 34059091, 2021). "Further, NLRP3 deficiency improved neurovascular damage in mice model following focal ischemic stroke via decreasing BBB damage and infarct volumes according to the evaluation of Evans blue permeability, magnetic resonance imaging (MRI), and electron microscopic analyses." (PMID 32581721, 2020). "The NLRP3 inflammasome, which consists of NLRP3, the apoptosis-associated speck-like protein containing a caspase-activating recruitment domain adaptor, and procaspase-1, has been linked to a number of diseases including ischemic stroke." (PMID 32788872, 2020). "One study from China suggested that genetic polymorphisms in NLRP3 may influence the risk of ischemic stroke in the Chinese population." (PMID 29850543, 2018). "Moreover, the activation of the NLRP3 inflammasome causes exacerbation of ischemic stroke and full-blown stroke, whilst the inhibition of NLRP3 inflammasome may ameliorate the clinical symptoms and diagnosis." (PMID 36676165, 2023). "Furthermore, the inhibition of inflammasome activation could have repercussions on other diseases, including diabetes, as NLRP3 inflammasome is involved in the pathogenesis of other diseases as well as in the neuroinflammation underlying ischemic stroke." (PMID 36297283, 2022). "The 29940 G>C genetic variation in the 3′-UTR of NLRP3 attenuated the stability and expression of NLRP3 mRNA in a gain-of-function manner, which resulted in susceptibility to several inflammation-related disorders, such as asthma, ischemic stroke and rheumatoid arthritis." (PMID 34172780, 2021). "In the current study, we intended to determine whether pretreatment with Gen could reduce the damage induced by ischemic stroke in reproductively senescent mice and to explore the underlying role of the NLRP3 inflammasome in the postmenopausal neuroprotection of Gen." (PMID 32625078, 2020). "Besides, it was reported that polymorphism of the NLRP3 gene may affect the risk of ischemic stroke via changing plaque vulnerability in the Chinese population." (PMID 32581721, 2020). "We propose that the NOD-like receptor protein-3 (NLRP3) inflammasome, which has been linked to inflammatory responses in models of ischemic stroke and various inflammatory diseases, may be one mechanism by which connexin hemichannel opening especially mediates perinatal brain injury." (PMID 30873043, 2019). "Moreover, NLRP3 deficiency ameliorates neurovascular damage in experimental ischemic stroke." (PMID 27127546, 2016). "Substantial evidence indicates that hyperglycaemia robustly enhances NLRP3 inflammasome assembly, thereby aggravating HT and worsening clinical outcomes after ischemic stroke." (PMID 41408503, 2025). "The NLRP3 inflammasome is a multiprotein complex that becomes activated following ischemic stroke, promoting the maturation and release of IL-1β and IL-18, thereby exacerbating neuroinflammation." (PMID 41451205, 2025).
ischemic stroke (continued). "Based on the results of this review, genistein is able to modulate several molecular targets, including Nrf2, NF-κB, and NLRP3, which play a major role in alleviating neuronal injury induced by ischemic stroke." (PMID 41433336, 2025). "This study underscores the significant therapeutic potential of the herbal mixture Astragalus mongholicus (AM) and Scutellaria baicalensis (SB) in mitigating inflammation and pyroptosis via modulation of the NLRP3/Caspase-1/GSDMD pathway in ischemic stroke." (PMID 39859214, 2025). "The application of transcutaneous electrical acupoint stimulation can effectively suppress neuroinflammation by modulating the Sirt1/NLRP3 signaling pathway following ischemic stroke, thereby mitigating cerebral injury." (PMID 40160465, 2025). "STING also activates pyroptosis via interactions with the NLRP3 inflammasome in microglia during ischemic stroke." (PMID 39602084, 2025). "Diels [Apiaceae; A. sinensis radix] modulates inflammatory and autophagic pathways, inhibits NLRP3 inflammasome activation, and prevents microglial pyroptosis, offering neuroprotection in ischemic stroke." (PMID 41438511, 2025). "We further analyzed the relationship between serum NLRP3 levels at 24 h postoperatively and the clinical characteristics of elderly patients with ischemic stroke." (PMID 40417311, 2025). "In this study, we found a significant increase in serum NLRP3 levels at 24 h postoperatively in elderly patients with ischemic stroke who developed POCD." (PMID 40417311, 2025). "As an indirect inhibitor of the NLRP3 inflammasome, resveratrol has been shown to have protective benefits against ischemic stroke injury in earlier studies." (PMID 40272769, 2025). "We employed a combination of in vitro and in vivo experimental approaches to explore the impact of high glucose on NLRP3 inflammasome activation and its consequences on ischemic stroke outcomes." (PMID 41254936, 2025). "Increasing evidence suggested that NLRP3 played a significant physiological and pathological role in the development of ischemic stroke." (PMID 40417311, 2025). "Further, a recent study demonstrated that HIF- 1α mediates NLRP3 inflammasome-dependent cell death following ischemic stroke." (PMID 40272769, 2025). "For the prevention and treatment of ischemic stroke, it is imperative to investigate the NLRP3 inflammasome further as a potential therapeutic target." (PMID 40606597, 2025). "This study investigates the effects of subclinical doses of esketamine on serum NLRP3 levels and early cognitive dysfunction in elderly ischemic stroke patients after neurointerventional procedures under general anesthesia." (PMID 40417311, 2025). "The nucleotide-binding oligomerization domain-like receptor protein 3 (NLRP3) and the caspase-1-mediated pyroptosis pathway play pivotal roles in ischemic stroke-induced brain injury." (PMID 39690856, 2025). "Previous reports indicated that high-intensity interval training and moderate-intensity continuous training inhibit the expression of NLRP3 inflammasome components and ischemic stroke-induced pyroptosis." (PMID 40691224, 2025). "Following the onset of ischemic stroke, hyperglycemia can lead to brain edema through the activation of the NLRP3 inflammasome, worsening neurological outcomes and increasing rates of mortality and disability." (PMID 40395813, 2025). "MCC950, a potent inhibitor of the NLRP3 inflammasome, significantly reduces levels of IL-1β and IL-18 in brain tissue and attenuates neutrophil infiltration in mouse models of ischemic stroke." (PMID 41451205, 2025). "This indicates that TXNIP plays a critical role in promoting NLRP3 inflammasome activation during ischemic stroke." (PMID 39690856, 2025). "Our results showed that the KG diet fed reduced inflammation by inhibiting the activation of NLRP3 inflammasomes against ischemic stroke." (PMID 40272769, 2025).